TNF (tumor necrosis factor)
Diseases named in the same sentence as TNF in open-access papers (continued):
Sharing a sentence is not in itself a finding about the gene and the disease.
Insulin resistance (continued). "Interestingly, we found that AIP1 deficiency in adipocytes increased the protein level of TNF-α, together with higher sugar level in the supernatant, indicating that AIP1 deficiency partially increases insulin resistance via TNF-α." (PMID 35712257, 2022). "Both in vitro and in vivo studies have reported the regulation of PAI-1, SAA, and CRP expression to be closely influenced by the pro-inflammatory cytokines, TNF-α, IL-1β and IL-6, as well as hormones such as GCs which are also associated with insulin resistance and T2D." (PMID 35883605, 2022). "Previous investigations have revealed that proinflammatory cytokines such as TNF-α and IL-6 could impair insulin signaling, which may cause insulin resistance." (PMID 34371867, 2021). "TNF-α is an inflammatory cytokine that has been linked to the development of insulin resistance." (PMID 34944525, 2021). "Hyperglycemia in severely ill, non-diabetic patients is believed to be caused by the cytokines (interleukin (IL)-1β and tumor necrosis factor (TNF)-α) that induce insulin resistance, and by hepatic gluconeogenesis driven by glucagon, catecholamines, cortisol, and growth hormone." (PMID 34202952, 2021). "Increasing levels of inflammatory cytokines specially TNF-α are at the heart of inflammatory cascades linked to insulin resistance, as we observed in present study in which levels of TNF-α and IL-6 were significantly higher in diabetic and pre-diabetic patients compared to healthy controls." (PMID 34077450, 2021). "Insulin resistance has been associated with elevated levels of TNF-α in RA patients." (PMID 35056068, 2021). "Insulin resistance is associated with an increase of TNF-α, IL-1α, IL-1β, IL-6, and leptin." (PMID 34970568, 2021). "TNF-α is responsible for a range of intracellular signaling systems, including the activation of NF-κβ, and has been linked with the increased activity of Jun N-terminal kinase, which is essential in promoting hepatic insulin resistance." (PMID 34943134, 2021). "Inflammatory cytokines such as IL-6 and TNFα can also cause insulin resistance, apoptosis, and dysfunction of mitochondria, which are involved in energy production, excessive production of reactive oxygen species, and the acceleration of muscle protein breakdown to eventually result in sarcopenia." (PMID 34575208, 2021). "In addition, in the major glucose deposition organ fat tissue, the pro-inflammatory cytokine TNFα can directly block the insulin receptor signaling pathway to cause insulin resistance and glucose intolerance." (PMID 34276421, 2021). "According to our network pharmacology analysis, SZ may function on NAFLD through regulating pathways associated with insulin resistance (IR), TNF-α, endoplasmic reticulum stress, oxidative stress, and hepatocyte apoptosis." (PMID 33505505, 2021). "This study was carried out to address whether splenic TNF-α level regulated by vagus nerve-related anti-inflammatory activity contributes to exercise-associated insulin resistance improvement in HFD mice." (PMID 34717724, 2021). "Interestingly, IL-6, IL-1, and TNF-α, which have been associated with insulin resistance and atherosclerosis, are also among the cytokines which play a role in the pathogenesis of vitiligo, possibly highlighting a link between these two conditions." (PMID 34445526, 2021). "Moreover, miRNA 221 was associated with both the synthesis of TNF and the development of insulin resistance." (PMID 34207683, 2021). "In this study, we focused on the effects of CCL4 inhibition on the levels of TNF-α and IL-6, which may be related to the root causes of insulin resistance in type 2 diabetes." (PMID 33968046, 2021). "TNFα plays a crucial role in the metabolic alteration that occurs in cancer cachexia, causing an increase in expenditure of energy, altered lipid and carbohydrate metabolism and insulin resistance." (PMID 33525436, 2021).
Insulin resistance (continued). "However, adipose tissues have been implicated in the release of inflammatory mediators such as interleukin-6 and tumor necrosis factor α, and also linked to the cause of insulin resistance." (PMID 34421824, 2021). "Tumor necrosis factor α (TNF-α), resistin, and interleukin-6 (IL-6) were linked previously to insulin resistance, while adiponectin was found to enhance insulin sensitivity, increase glucose transepithelial transport, lower glucose synthesis in the liver, and suppress IL-6 and TNF-α." (PMID 35095801, 2021). "Moreover, adipose tissue produces tumor necrosis factor-alpha (TNFα), the activation of which is associated with insulin resistance via the reduced expression of insulin-sensitive glucose transporters." (PMID 33810367, 2021). "Similarly, e-WAT from HFF rats exhibited increased TNF-α content, in agreement with the frequent association between insulin resistance and inflammation." (PMID 31991770, 2020). "This study allowed one to conclude that the inactive and sedentary lifestyle of female adolescents, along with excess body fat, insulin resistance, and higher concentrations of high-sensitivity C-reactive protein are associated to the higher concentration of TNF-α, IL-6, and leptin." (PMID 32694929, 2020). "Analysis of the interactions of differentially expressed microRNAs with gene expression pathways suggests the potential contribution of selected miRNAs in the regulation of the activity of genes associated with insulin resistance, fatty acids metabolism, and adipocytokine (TNF-α, leptin) signaling." (PMID 32069846, 2020). "This may be because hepatitis B virus infection could cause insulin resistance, potentially via tumor necrosis factor alpha (TNF-α)." (PMID 32155166, 2020). "Specific inflammatory molecules such as TNFα, IL-6, and other inflammatory signaling pathways identified with COVID-19 have been associated with the pathogenesis of type 2 diabetes mellitus and malaria through insulin resistance." (PMID 33134395, 2020). "TNF-alpha is strongly correlated with lipolysis and this cytokine causes insulin resistance." (PMID 32454912, 2020). "In our study, TNF-α level was associated with hyperglycemia, insulin resistance, and dyslipidemia, and MCP-1 level was associated with CRP level, but TNF-α and MCP-1 levels were not independent contributors to diabetes progression after adjustment for metabolic parameters." (PMID 31690939, 2020). "In addition, high levels of serum TNF-α and IL-6 have shown to be linked to obesity and insulin resistance which are key players in metabolic syndrome." (PMID 33344519, 2020). "Chronic inflammation is implicated in visceral obesity and exacerbates insulin resistance, which is characterized by the abnormal production of adipocytokines such as tumor necrosis factor-α (TNF-α), interleukin-1 (IL-1), IL-6, leptin, and plasminogen activator inhibitor-1 (PAI-1)." (PMID 32478050, 2020). "As TNFα and IL-6 also potentially induce insulin resistance, stimulate the production of androgen, and cause hypothalamic-pituitary-ovarian axis secretion disorder, a concomitant PCOS condition may result in a vicious cycle." (PMID 32256193, 2020). "Further studies found that TNFα can perturb insulin signaling, causing insulin resistance." (PMID 32183037, 2020). "Analysis of the interactions of differentially expressed microRNAs with gene expression pathways suggests the potential contribution of selected miRNAs to the regulation of the activity of genes associated with insulin resistance, fatty acids metabolism, and adipocytokine (TNF-α, leptin) signaling." (PMID 32069846, 2020). "TNF-α produced by tissue-resident macrophages causes metabolic syndrome and insulin resistance." (PMID 33076522, 2020).
Insulin resistance (continued). "Herein, we investigated the effect of EWH and egg white-derived peptide, IRW, on TNF-α-induced insulin resistance and its underlying molecular mechanism by testing glucose uptake, GLUT4 translocation, and insulin-signaling pathway using rat skeletal muscle cells (L6)." (PMID 29955954, 2019). "However, reduced insulin resistance, caused by reducing the expression of tumor necrosis factor (TNF)-α and interleukin (IL)-6 and inhibited M1 pro-inflammatory macrophage infiltration in adipose tissue, was suggested as a potential mechanism." (PMID 30735525, 2019). "Since this receptor can be activated by saturated fatty acids, which are associated with higher risk of developing T2D, a pathway involving TLR4, TNFα, and insulin resistance could be a mechanistic link between T2D and depression yet to be explored." (PMID 30837902, 2019). "Elevated levels of the pro-inflammatory cytokine TNF-α is associated with insulin resistance." (PMID 30871083, 2019). "Also, the G7G genotype of TNF-alpha 308 G/A polymorphism increases insulin levels and insulin resistance among women with gestational diabetes." (PMID 31828161, 2019). "Furthermore, IL-1β modulated by TNFα in mouse adipocytes has been reported to cause hepatic insulin resistance." (PMID 30958839, 2019). "The molecular mechanism underlying TNF-α-mediated insulin resistance is well recognized." (PMID 29955954, 2019). "Insulin resistance can also impact tissues of the joint organ system, because insulin resistance has been linked to chondrocyte dysfunction, and insulin appears to have a protective role for synoviocytes, whereby insulin blunts TNF-induced matrix metalloproteinase release." (PMID 29527173, 2018). "In addition, serum AGEs have been shown to stimulate TNF-α in monocytes, which causes insulin resistance." (PMID 29996539, 2018). "Inflammatory cytokines IL-6 and TNF-α have been implicated in insulin resistance." (PMID 30526660, 2018). "The increases in monocyte TLR4 and phosphorylated JNK and p38 levels caused by lipid infusion were associated with enhanced production of multiple cytokines, including IL-1β, IL-6, MCP-1, and TNFα, all of which have been implicated in insulin resistance and type 2 diabetes." (PMID 29649324, 2018). "TNF-α is one of proposed molecules that can cause insulin resistance during pregnancy." (PMID 29387323, 2018). "In T2DM, the c-Jun N-terminal kinase (JNK) pathway is stimulated by the TNF-α cascade, thereby initiating peripheral insulin resistance, causing IRS-1 inhibition at the brain level and the interruption of downstream cascade favoring tau hyperphosphorylation and amyloid assembly." (PMID 30154946, 2018). "In conclusion, the adiponectin/TNF-α ratio might be more informative than diponectin and TNF-α alone for predicting women with high risk of insulin resistance and metabolic syndrome in pregnancy." (PMID 29387323, 2018). "Inflammation and insulin resistance are closely linked, and inflammatory cytokines such as tumor necrosis factor alpha (TNFα) may inhibit insulin signaling and promote insulin resistance." (PMID 29576769, 2018). "Higher overall adiposity levels are associated with increased IL-6, TNF-α, and leptin expression, and lower adiponectin expression, which all could promote an insulin resistance state." (PMID 29867770, 2018). "Increases in IL-1β, IL-6, and TNF-α are associated with insulin resistance and glucose intolerance." (PMID 28420148, 2017). "Moreover, several studies have shown an association between insulin resistance with elevated TNF-α level." (PMID 28832656, 2017). "In addition, hepatic inflammation and fibrosis are also linked to adipose inflammation and insulin resistance, through a release of inflammatory mediators such as TNF-α, IL-6, and monocyte chemoattractant protein-1 (MCP-1) from adipose tissue." (PMID 28759632, 2017). "The further measurements of IL-1beta/IL-1ra or TNF alpha which are associated with insulin resistance may be useful." (PMID 28353655, 2017).
Insulin resistance (continued). "TNF-α could reduce insulin sensitivity to its receptor and then be implicated in the process of insulin resistance, ultimately exacerbating liver steatosis." (PMID 28349964, 2017). "Since TNF-α contributes to many pathogenic processes, including insulin resistance and carcinogenesis, through both autocrine and paracrine mechanisms, it is possible that LPS-induced TNF-α secretion by myoblasts might also play a role in muscle wasting." (PMID 28742154, 2017). "In the meantime have a number of studies also suggested that development of insulin resistance may be induced by sympathetic activity based on associated TNFα contribution." (PMID 27147943, 2016). "TNF-α is an inflammatory cytokine that is known to cause insulin resistance." (PMID 26930407, 2016). "Specifically, hepatic macrophages, which consist of resident KCs and recruited bone marrow-derived macrophages, are the major cells that produce inflammatory mediators, such as tumor necrosis factor (TNF)-α and interleukin (IL)-1β, causing systemic insulin resistance and, ultimately, NASH." (PMID 27347998, 2016). "The host immune response to H. pylori infection is complex and involves up regulation of several pro-inflammatory cytokines, such as C-reactive protein (CRP), interleukin 6 (IL-6), and tumor necrosis factor- α (TNF-α), which are implicated in insulin resistance and the development of diabetes." (PMID 27148410, 2016). "Elevated TNFα is linked to insulin resistance in humans and animals." (PMID 27669293, 2016). "Furthermore, inflammatory cytokine levels, including high TNF-α, high leptin levels, and low adiponectin levels, are associated with insulin resistance in obese children and also affect physical activity during the growth and maturation process." (PMID 26011530, 2015). "Inflamed and abnormally differentiated adipocytes are, on the other hand, a source for pro-inflammatory cytokines (e.g. TNFα, interlukin-8) and adipokine (e.g. leptin) which predispose to atherosclerosis and further aggravation of insulin resistance and diabetes." (PMID 25714093, 2015). "TNFα causes insulin resistance by direct inhibition of insulin receptor tyrosine kinase activity." (PMID 26041981, 2015). "Incubation of adipocytes with TNFα caused insulin resistance and a concomitant reduction in TUSC5." (PMID 26240143, 2015). "In addition insulin resistance was associated with circulating levels of TNF-α (T = 2.76, p = 0.009) and circulating levels of IL-6 (T = 2.81, p = 0.008)." (PMID 26061745, 2015). "Insulin resistance might be caused by pro-inflammatory cytokines, and we found that IL-6, TNF-α and IL-1β were up regulated in aged male GADD34-deficient mice." (PMID 26316333, 2015). "TNFα is elevated in obesity and positively associated with insulin resistance." (PMID 26106437, 2015). "Cytokines, as IL-6 and TNF-alpha, are elevated in diabetic patients, suggesting that the pattern of circulating inflammatory cytokines modifies the risk for diabetes and is correlated with insulin resistance." (PMID 25922592, 2015). "Additionally, increased insulin resistance has been found to be associated with increased levels of inflammatory cytokine TNF-a and increased levels of inflammation as shown in the integrated model in pathway: 7-27-48-14-54-69-70-88-50-41-inflammatory state." (PMID 26231223, 2015). "What is the mechanism underlying PP4 involvement in TNF-α-induced hepatic insulin resistance?" (PMID 26666849, 2015). "Given that an ANP-mediated reduction of TNF-α, IL-6 and IL-1β have been linked to reduced insulin resistance, the suppression of these cytokines and potentiation of HO-adiponectin-ANP axis is important for enhanced glucose metabolism and improved kidney function observed in ZDFs." (PMID 24498225, 2014). "Moreover, without affecting insulin receptor-mediated signal transduction, TNF-α can induce insulin resistance in adipocytes, characterized by loss of insulin receptor substrate-1 and GLUT4 expression." (PMID 24465695, 2014).
Insulin resistance (continued). "Another study showed that ROS-induced insulin resistance caused by TNF-α and dexamethasone could be reversed by suppression of ROS via antioxidants and transgenes promoting antioxidant defense." (PMID 25101238, 2014). "Also, have been shown that TNF-α and IL-6 cause systemic insulin resistance through activation of MAP kinases, protein kinase C (PKC) and SOCS-3 mediated proteasome degradation." (PMID 24966877, 2014). "TNF-α is one of candidate molecules responsible for causing insulin resistance during pregnancy." (PMID 25202741, 2014). "Reports indicate that anti-TNF is independently associated with a lower CV risk due to the fact that it reduces CV events in young patients by improving the lipid profile, insulin resistance, endothelial function, and aortic compliance and decreasing progression rates of subclinical AT." (PMID 25177690, 2014). "According to previous data, our results indicate that the induction of proinflammatory cytokines, IL-6 and TNF-α production, caused in PBMs stimulated by LPS, is similar to that observed in obese subject, where metabolic disorders, proinflammatory state and insulin resistance are often associated." (PMID 25368579, 2014). "WC is strongly associated with sarcopenic obesity and insulin resistance, both of which are related to functional decline, frailty and disability, and thought to be partially mediated by an increase in pro-inflammatory markers, including IL-1, IL-6, and TNF-a." (PMID 25106459, 2014). "Alterations of NKT function might lead to overproduction of TNF-α, causing inflammation and insulin resistance." (PMID 23885277, 2013). "Consistent with this previous study, our results show that hyperleptinemia is significantly associated with high serum levels of TNF-α and IL-12, as well as reduced concentrations of IL-10 in subjects with central obesity, hyperglycemia, increased insulin resistance, and hypertriglyceridemia." (PMID 23986664, 2013). "TNF-α has been implicated in the pathogenesis of insulin resistance in vitro and in vivo." (PMID 23437347, 2013). "Soluble CD163 (sCD163) was shown to be associated with insulin resistance in humans and may be a more reliable measure of T2D than TNF-α; sCD163 secreted by macrophages should be examined further in the dolphin as well." (PMID 24101915, 2013). "TNF-α interferes on insulin metabolism cascade, activating proinflammatory pathways that impair insulin signalling at the level of the insulin receptor substrate proteins, causing insulin resistance." (PMID 23919592, 2013). "TNF-α is also implicated in a number of catabolic states linked to insulin resistance such as sepsis and cancer even though its exact mechanism of actions remains unclear." (PMID 24391675, 2013). "Inflammation and insulin resistance are closely linked and inflammatory cytokines such as tumor necrosis factor (TNF), interleukin (IL)-6, IL-1 and IL-8 may inhibit insulin signaling by multiple mechanisms." (PMID 22691241, 2012). "Although our results suggest a beneficial effect of anti-TNF treatment on insulin signaling in RA patients with high insulin resistance, the clinical importance of such treatment in reducing risk of cardiovascular disease in the long term remains to be determined." (PMID 22691241, 2012). "Also, we did not include other inflammatory markers, for example, TNF-α and TNF-modifying mediators in this study, thus we cannot exclude that some confounders related to both IL-6 and insulin resistance are affecting the associations we investigated." (PMID 22272193, 2012). "Our observations are consistent with these findings and indicate that the decreased insulin sensitivity observed following FTox-G50 injection is mediated by an increase in the TNF-α concentration in adipose tissue, which selectively stimulates the expression of Map4k4 to cause insulin resistance." (PMID 22816003, 2012).